IL10 (interleukin 10)
Diseases named in the same sentence as IL10 in open-access papers (continued):
Sharing a sentence is not in itself a finding about the gene and the disease.
tumor (continued). "Tumor‐targeting bacteria can be engineered to continuously, specifically, and exclusively release IL‐10 within tumor cells, thereby becoming potential immunotherapeutic targets." (PMID 41574027, 2026). "Tumor-associated macrophages and microglia reportedly comprise up to fifty percent of the tumor mass and frequently exhibit an M2-like phenotype, secreting IL-10 and TGF-β to inhibit T-cell activity." (PMID 41596524, 2026). "This stable and efficient metabolic profile supports maintenance of the immunosuppressive phenotype, sustained secretion of inhibitory cytokines such as TGF‐β and IL‐10, and promotion of tumor angiogenesis and immune escape." (PMID 41426206, 2026). "Gender, TNM stage, and tumour site were considered along with IL10 for the multivariate PFS/OS models in advanced disease." (PMID 41249451, 2026). "Under the hypoxic conditions generated by rapid tumor cell proliferation, TAMs predominantly shift toward the M2 phenotype and upregulate IL‐10, VEGF, and HIF‐1α, contributing to cancer metastasis and an increasingly immunosuppressive TME." (PMID 41426206, 2026). "Daily intragastric administration of Pt517 significantly inhibited tumor growth in mice; increased the expression levels of TNF-α, INF-γ, and CD8 in tumor tissues; and decreased the levels of IL-6, IL-10, and TGF-β." (PMID 42121906, 2026). "Bregs play a dual role in the tumor microenvironment in inhibiting or promoting immune responses by secreting cytokines such as IL-10, IL-35, and TGF-β." (PMID 41614936, 2026). "Phenotypic analyses revealed that tumor-infiltrating CD301b+ cells are predominantly type 2 conventional dendritic cells (cDC2s) and exhibit IL-10 expression within the TME." (PMID 42147159, 2026). "BALF data obtained during routine clinical care were retrospectively collected for tumor markers (CEA, CYFRA21-1, NSE, ProGRP), cytokines (IL-6, IL-8, TNF-α, IL-10), ctDNA mutation profiles, and immune-cell subpopulations." (PMID 41970393, 2026). "Conversely, M2-TAMs are activated by T helper 2 (Th2) cytokines, such as interleukin-4 (IL-4), interleukin-10 (IL-10), macrophage colony-stimulating factor (M-CSF), or tumor cell-surface molecules 27-29." (PMID 41328341, 2026). "Bregs in the TME promote tumor growth by secreting immunosuppressive factors, such as IL-10, TGF-β, and IL-35, which inhibit the activity of T cells and create an immunosuppressive microenvironment." (PMID 41614936, 2026). "IL-10, produced by Tregs, tumor cells, or even the macrophages themselves in an autocrine loop, activates STAT3, reinforcing an M2, anti-inflammatory cascade." (PMID 41597210, 2026). "Tumor-derived exosomes (MC38-Exos) directly induced an immunosuppressive Breg phenotype by upregulating IL-10 and TGF-β." (PMID 41614936, 2026). "We elucidate how the maturation status of TLSs dictates the functional plasticity of TIL-Bs, switching between anti-tumor effector phenotypes (e.g., antibody-secreting plasma cells) and pro-tumor regulatory roles (e.g., IL-10+ regulatory B cells)." (PMID 41799207, 2026). "For example, they potently restrain anti-tumor immunity by releasing immunosuppressive factors such as IL-10 and TGF-β1, generating ROS, and expressing immune checkpoint ligands to inhibit the effector function of T cells and NK cells." (PMID 41516400, 2026). "In this setting, interleukin-10 (IL-10) has attracted growing attention due to its complex, context-dependent roles in immune regulation and tumor immune tolerance." (PMID 42193416, 2026). "BCG induces high production of IL-10 by monocytes which is several-fold reduced by phagocytosis of tumor antigens." (PMID 41836405, 2026). "Immunohistochemistry results revealed that compared with CD20+ B cells in mice receiving NC-B cells, CD20+ B cells in the caecal orthotopic tumours of mice receiving adoptive transfer of SENP7-overexpressing B cells exhibited higher levels of IL-10 expression." (PMID 41362746, 2026).
tumor (continued). "Tumor‐derived IL‐10 promotes immunosuppression, whereas IL‐10R signaling can sustain functional memory‐like subsets." (PMID 41368078, 2025). "For instance, studies have shown that IL-10 can promote immune evasion in advanced cancers, potentially contributing to tumor aggressiveness." (PMID 40227503, 2025). "These macrophages directly promote tumor metastasis by secreting immunosuppressive factors (e.g., IL-10, TGF-β) and pro-angiogenic factors (e.g., VEGF)." (PMID 41246334, 2025). "They suppress anti-tumor immune responses through secretion of IL-10, IL-35, and TGF-β, and via expression of immune checkpoint molecules such as CTLA-4 and LAG-3." (PMID 41244711, 2025). "M2-type TAMs accelerate tumor progression and invasion through the secretion of factors such as interleukin-10 (IL-10) and transforming growth factor beta (TGF-β)." (PMID 40332367, 2025). "Serum cytokines, such as TNF-α, IL-6, and IL-10, reflect inflammation and the tumor microenvironment." (PMID 41226541, 2025). "Because of its immunosuppressive effects, IL-10 up-regulation is a common feature of tumor progression and metastasis." (PMID 39841829, 2025). "Regulatory T cells, myeloid-derived suppressor cells (MDSCs), and tumor-associated macrophages secrete immunosuppressive cytokines such as TGF-β and IL-10, which inhibit T-cell activity and promote an environment that favors tumor growth." (PMID 40001572, 2025). "MDSCs inhibit the anti-tumor activity of T cells through Arg-1, iNOS, ROS, and the anti-inflammatory cytokine IL-10." (PMID 39757995, 2025). "Given the known role of IL-12 in NK cell activation during tumor immunity, it is possible that IL-10 produced by NK cells can act in an autocrine fashion to increase or maintain NK cell activity." (PMID 40410571, 2025). "A clinical and murine study in 2024 reported the elevation of immunosuppressive markers PD-L1 and IL-10 in immune cells (e.g., macrophages and dendritic cells) and tumor tissues from patients with advanced GC, compared to healthy individuals." (PMID 40357361, 2025). "IL-10, a key anti-inflammatory cytokine, further pushes macrophages toward an M2 profile while inhibiting M1-mediated anti-tumor activity." (PMID 40563651, 2025). "CRC tumors (tumor cells, Cancer-Associated Fibroblasts (CAFs) and the immune cells) release a range of immunosuppressive cytokines, including TGF-β, IL-10, and VEGF." (PMID 40236691, 2025). "TAMs can regulate the tumor microenvironment and impair T cell function by releasing immunosuppressive mediators, including IL-10, as well as various chemokines." (PMID 40630800, 2025). "IL-10 is an important immunosuppressive cytokine that is frequently upregulated in the tumor microenvironment." (PMID 39187677, 2025). "Under the distinctive pathophysiological conditions of the TME, cancer-associated inflammatory cytokines, including TNF-α, TGF-β, IFN-I, IL-1, IL-6, and IL-10, often exhibit upregulated expression, thereby modulating the biological behaviors of tumor cells." (PMID 40563367, 2025). "We also assessed phagocytosis of tumor cells by flow cytomtery by macrophages that were polarized to M1 or M2 with either IFNγ or IL-10 respectively." (PMID 40078999, 2025). "Similar immunosuppressive strategies are observed with other tumor-secreted factors such as IL-10, VEGF, G-CSF and IL6, which likewise limit APC activation and T cell-mediated anti-tumor immunity." (PMID 41488634, 2025). "In preclinical studies, CmAb-(IL10), a bispecific fusion protein, has demonstrated superior anti-tumor activity compared to IL10 fused with a non-tumor-specific antibody." (PMID 40612864, 2025). "Multiple cytokines, including IL-2, IL-12, IL-10, and IL-4, showed significant reduction in tumor tissues derived from Gsdmd–/– mice compared with WT mice." (PMID 40759573, 2025). "In hypoxic environments, tumor cells also secrete immunosuppressive cytokines, such as IL-10 and TGF-β, which play pivotal roles in shaping the TME." (PMID 40322886, 2025).
tumor (continued). "Immunosuppressive cytokines such as TGF-β, IL-10, and IL-6, secreted by cancer cells, CAFs, and TAMs, modulate the immune system, leading to its suppression and promotion of tumor development." (PMID 40362280, 2025). "Conventional T cells are converted to CD4 + CD25highFoxP3+ Treg cells in a way that is reliant on TGFβ1 and IL10 since neutralizing antibodies specific to TGFβ1 and/or IL10 prevents tumor-derived EVs from proliferating Treg cells." (PMID 40407494, 2025). "Mitochondrial respiratory complex III sustains IL-10 production in macrophages and promotes tumor-mediated immune evasion." (PMID 39841829, 2025). "Molecularly, Tregs in the TME of TNBC secrete immunosuppressive cytokines such as TGF-β and IL-10, which further enhance the immunosuppressive environment and promote tumor growth." (PMID 40281554, 2025). "The release of IL-10 by TAMs additionally hinders the antigen presentation capability of DCs, thereby impeding tumor immunity." (PMID 40079015, 2025). "MDSCs promote tumor immune escape by secreting factors like IL-10 and TNF-β, downregulating the TCR-related ζ chain, or recruiting Tregs to inhibit T cell activation." (PMID 40427733, 2025). "Within the TME, Tregs can suppress the functions of other T cells by secreting tumor growth factor-beta (TGF-β), interleukin-10 (IL-10), and IL-35, which suppress antigen presentation in the tumor and decrease anti-tumor immune responses." (PMID 40508074, 2025). "They suppress the function of effector T-cells by secreting immunosuppressive factors (such as TGF-β and IL-10), which, in turn, promotes tumor immune evasion." (PMID 40557321, 2025). "These cells primarily suppress CD8+ T cell function by secreting immune-suppressive factors such as IL-10 and TGFβ, facilitating tumor immune evasion." (PMID 40098971, 2025). "This encompasses maintaining effector T cell function, promoting IL-12 production, reducing IL-10 secretion by dendritic cells, and decreasing tumor-infiltrating Tregs." (PMID 40966256, 2025). "TAMs facilitate immune evasion by secreting IL-10, inducing T cell apoptosis via CD120a/b, altering tumor cell phenotypes, and overexpressing B7-H3 via EGFR/MAPK, inhibiting CD8+ T cells." (PMID 40443678, 2025). "IL-10 can inhibit the production of IL-2 by T cells and suppress the antitumor immune response, thus making the tumor further deteriorate (Arany, Grattendick, & Tyring, 2002)." (PMID 41399789, 2025). "In contrast, M2 macrophages, driven by IL-4, IL-10, and TGF-β, are associated with tumor progression via immunosuppression, angiogenesis, and tissue remodeling." (PMID 40330466, 2025). "Clinically, elevated TGF-β and IL-10 in circulation and tumor tissues reflect Treg-mediated immunosuppression." (PMID 41181112, 2025). "Th2 and Tregs release cytokines that assist tumor progression and metastasis, such as IL‐10 and TGF‐β and are therefore considered a pro‐tumor subset." (PMID 40257446, 2025). "Our findings reveal that lidocaine modulated the anti-tumor effects by decreasing IL-10, TGF-β, and IL-35 levels in CD4+CD25+Foxp3+TIICs, decreasing PD-1, and increasing IFN-γ expression in cytotoxic CD8+TIICs through the NF-kb pathway." (PMID 40244064, 2025). "IL-10 can promote immune evasion by tumor cells by inhibiting the activation and function of effector T cells, NK cells, and macrophages." (PMID 40484866, 2025). "By suppressing T cell anti-tumor activity through the release of immune-suppressing proteins like IL-10 and IL-4, the M2-like TME promotes tumor growth by relying on oxidative phosphorylation (OXPHOS) and fatty acid oxidation (FAO)." (PMID 41451233, 2025). "While it is associated with immunosuppression, particularly through inhibition of Th17 cells and modulation of macrophage activity, there is evidence suggesting that IL-10 can also contribute to anti-tumor immune responses under certain conditions." (PMID 39931062, 2025).
tumor (continued). "In contrast, M2 macrophages, induced by IL-4, IL-10, and IL-13, support tumor growth, suppress immune responses, and facilitate tissue remodeling." (PMID 40563651, 2025). "In contrast, other cytokines, such as interleukin-6 (IL-6), interleukin-8 (IL-8), transforming growth factor-beta (TGF-β), and interleukin-10 (IL-10) have immunosuppressive effects and contribute to tumor progression." (PMID 40867268, 2025). "By producing cytokines including transforming growth factor-beta (TGF-β) and IL-10, which encourage immune-suppressive traits in neutrophils, macrophages, and cytotoxic T cells, regulatory B-cells encourage tumor aggression." (PMID 40230883, 2025). "TME is dominated by M2 macrophages, on the other hand, which suppress the efficacy of M1 cytotoxicity and promote tumor progression by secreting high levels of cytokines, such as interleukin-10 (IL-10) and transforming growth factor beta (TGF-β)." (PMID 40872479, 2025). "In the HNSCC TME, tumor cell–derived cytokines and chemokines including IL-6, IL-10, and CCL2 can drive polarization of TAMs toward the M2 phenotype." (PMID 40231472, 2025). "Mechanistically, GABA promotes the differentiation of monocytes into anti-inflammatory macrophages that secrete IL-10, which in turn inhibits the anti-tumor function of CD8+ T cells." (PMID 41285707, 2025). "For instance, sulfated fucoidan SHPPB2 from Sargassum fusiforme stimulates splenocyte proliferation and induces anti-inflammatory cytokine production (IL-2, IL-4, IL-10) in tumor-bearing rats." (PMID 41149588, 2025). "On the other hand, some tumor cells produce IL-10, which promotes plasma cells to generate IgG4, enhances the function of Treg cells, induces a Th2-type immune environment, and helps tumor immune evasion." (PMID 41301426, 2025). "The next cytokine produced by Th2 lymphocytes, IL-10, is primarily known for its ability to downregulate anti-tumour immunity." (PMID 39325360, 2025). "IL-10, produced by both tumor cells and tumor-infiltrating immune cells, primarily acts by suppressing the activation and function of APCs and promoting the differentiation of Tregs." (PMID 41007114, 2025). "We observed that the soft matrix dependent dedifferentiation of tumor tissue led to upregulation of IL-10 and TGF-β, which are well known mediators of immunosuppression." (PMID 40425576, 2025). "IL-10 can inhibit the production of inflammatory mediators, thereby reducing the severity of the inflammatory response, while also possessing tumor-promoting effects." (PMID 39795037, 2025). "Tumor cell-derived HMGB1 has been shown to induce regulatory T cells (Tregs) to produce IL-10, which in turn suppresses CD8+T cell-dependent antitumor immunity." (PMID 40169575, 2025). "These PD-L1+ TAMs are activated by tumor-derived IL-10 and mediate CD8+ T cell dysfunction through the PD-1/PD-L1 interaction." (PMID 40308604, 2025). "These TAMs secrete cytokines such as TGF-beta and IL-10, promoting tumor growth and suppressing tumor immunity, thus forming part of the tumor microenvironment." (PMID 40226611, 2025). "Overall, we confirmed that M2‐like macrophages induce the expression of SPI1 on tumor cells through IL8/IL10 to promote ITGβ8 transcription." (PMID 39535362, 2025). "Hyaluronan carried by tumor-derived microvesicles induces IL-10 production in classical (CD14++CD16−) monocytes via PI3K/Akt/mTOR-dependent signaling pathway." (PMID 40328660, 2025). "M2 macrophages secrete various cytokines such as transforming growth factor-β (TGF-β) and interleukin-10 (IL-10), which suppress the anti-tumor activity of T cells and Natural Killer (NK) cells and, thus, promote tumor cell growth." (PMID 41551601, 2025). "Although B cells mainly exert anti-tumor effects, regulatory B cells (Bregs) possess immunosuppressive functions by secreting cytokines such as IL-10, IL-35, and TGF-β, together with adenosine and granzyme B." (PMID 40908470, 2025).
tumor (continued). "IL-10 hinders anti-tumor responses of NK cells but it also suppresses the release of Th1 mediators from eosinophils." (PMID 41155334, 2025). "LRMs are recruited to the tumor mass, where the local microenvironment, rich in factors like IL-10 and TGF-β, reprograms them into tumor-associated macrophages (TAMs)." (PMID 41293237, 2025). "These immune cells, particularly TAMs, can promote tumor growth and metastasis by secreting various cytokines (e.g., IL-10, TGF-β, etc.)to maintain an immunosuppressive status in the TME." (PMID 41376630, 2025). "In contrast, M2-like macrophages facilitate immunosuppression and immune escape during tumor progression by secreting anti-inflammatory cytokines, such as interleukin-10 (IL-10) and transforming growth factor-β (TGF-β)." (PMID 40426926, 2025). "Immunosuppressive cytokines like transforming growth factor-β1 (TGF-β1) and interleukin-10 (IL-10) contribute to the enhanced immunosuppressive condition of the tumor microenvironment." (PMID 41438510, 2025). "M2c macrophages, driven by IL-10, are involved in immune suppression and tissue remodeling, facilitating the immune evasion of tumor cells in TNBC and enhancing the metastatic potential of cancer cells." (PMID 40092996, 2025). "M2b macrophages, activated by immune complexes and LPS, are characterized by their anti-inflammatory profile, releasing IL-10 and IL-6, which dampen anti-tumor immunity." (PMID 40079009, 2025). "These B cells subsequently expand local Treg populations through the secretion of IL-10, establishing an immunosuppressive niche that supports tumor cell implantation and proliferation." (PMID 41280929, 2025). "By inhibiting these inflammatory cytokines IL-10 inhibits the activation of antigen-presenting cells, such as dendritic cells and macrophages, which are crucial for initiating anti-tumor immune responses." (PMID 40484866, 2025). "Key cytokines such as interleukin-6 (IL-6), TGF-β, and IL-10, produced by immune and stromal cells within the tumor microenvironment, play a critical role in promoting tumor growth and creating an immunosuppressive niche." (PMID 40002248, 2025). "Th2 cells are a subset of CD4+T cells that promote tumor progression by secreting cytokines such as IL-10 and IL-13 to enhance angiogenesis and inhibit the cytotoxic effects of CD8+ T cells." (PMID 41040664, 2025). "STAT3 subsequently transduces the signal, resulting in IL-6 and IL-10 production, therefore amplifying this chronic pro-inflammatory loop and inducing tumor growth." (PMID 41463071, 2025). "Potent anti-inflammatory and immunomodulatory properties of IL-10 bring broad prospects among clinical application, with clinical trials in areas such as rheumatoid arthritis, inflammatory bowel disease, tumor immunotherapy, and chronic viral infection." (PMID 41300695, 2025). "Data showed that sGRP78‐conditioned B cells upregulated their IL‐10 and PD‐L1 expressions, as well as B cells cocultured with drug‐treated tumor cells." (PMID 40936109, 2025). "Leal and John have suggested that TAMs promote tumor growth and immune escape by secreting cytokines and chemokines such as IL‐10 and CCL2." (PMID 41179708, 2025). "Immunosuppressive molecules such as IDO, PGE2, TGF-β, prostaglandins, and IL-10 from the tumor microenvironment inhibit NK cell activity and downregulate activating receptors." (PMID 41008790, 2025). "Mouse studies indicate that high concentrations of pegylated IL-10 can induce complete tumor rejection." (PMID 41142594, 2025). "M2 TAMs also the ability of tumor cells to evade adaptive immunity by secreting the immunosuppressive cytokines IL-10 and TGF-β." (PMID 40607405, 2025). "Depletion of regulatory T cells (Tregs), for instance, via low-dose cyclophosphamide, has been shown to improve anti-tumor responses in preclinical GBM models by reducing IL-10 production and enhancing effector T cell function." (PMID 41374974, 2025).